STAT3 (signal transducer and activator of transcription 3)
Diseases named in the same sentence as STAT3 in open-access papers (continued):
Sharing a sentence is not in itself a finding about the gene and the disease.
cervical tumor (12 papers, 2010 to 2025). "EGFR is also associated with the growth of tumor cells and functions as an immune-suppressor factor to promote cervical tumor growth through the STAT3 pathway." (PMID 40336816, 2025). "Strategies to inhibit or reduce STAT3 activation include the use of interfering STAT3 siRNAs, which reduce the resistance of cervical tumor cells to cisplatin treatment." (PMID 33076315, 2020). "Furthermore, HPV-positive cervical tumor cells produce high levels of interleukin 6 (IL-6) for autocrine signaling and to increase STAT3 activation." (PMID 35163748, 2022). "Additionally, HPV-positive cervical tumor cells are capable of producing large amounts of IL-6 for autocrine signaling and for increasing STAT3 activation." (PMID 33076315, 2020). "Taken together, our results suggest that TMS-TMF-4f may potentially inhibit human cervical tumor growth through the induction of apoptosis via STAT3 suppression." (PMID 31816985, 2019). "Cervical tumors, the best characterized HPV associated tumors, display systemic effects on the immune system, these are triggered, for example, by cytokines as G-CSF that promote leukocytosis by signaling through STAT3." (PMID 30840689, 2019). "MiR-125a inhibits the tumorigenesis and metastasis of cervical tumors by targeting STAT3." (PMID 26389681, 2015). "Experimental data in cervical tumor cells show that JAK2, STAT3, and STAT5 inhibitors reduce cell proliferation, induce apoptosis, and improve response to other drugs such as cisplatin." (PMID 33076315, 2020). "Proteins such as STAT3, TGFβ3, LEFTY A, PARP1, and ZFX are also expressed in cervical tumor samples." (PMID 31885625, 2019).
coronary artery disease (12 papers, 2016 to 2025). "Many authors describe a conflicting function of STAT1 and STAT3 in ischemic heart disease where STAT1 contributes to the loss of cardiomyocytes and STAT3 protects them from I/R injury." (PMID 32987855, 2020). "STAT1 and STAT3 have been shown to play roles in ischemic heart disease, and in our study, we found that a gene in the STAT family (STAT4) was a human-specific DEG." (PMID 34003819, 2021). "Additionally, it has been demonstrated that GPR4 facilitates EPC-induced angiogenesis by activating the signal transducer and activator of transcription 3 (STAT3)/vascular endothelial growth factor A (VEGFA) pathway in patients with coronary artery disease." (PMID 40563452, 2025). "However, cytoplasmic signal transducer and activator of transcription 3 is encoded by STAT3 dampens macroautophagy by repressing EIF2AK2/PKR activity, while its gene expression is also increased dramatically in patients with coronary artery disease." (PMID 34012683, 2021). "This association is further underscored by recent reports describing that glucose over-utilization drives the excessive production of IL-6 and IL-1β by monocytes and macrophages derived from patients with coronary artery disease, by a process that is dependent on redox-sensitive STAT3 signaling." (PMID 32350546, 2020). "Of interest, STAT3 is required for Flt3-dependent formation of DCs from bone marrow derived cells, and plays an important role in production of IL-1β, IL-6, and TNFα in macrophages of humans with coronary artery disease." (PMID 29800237, 2018).
cutaneous squamous cell carcinoma (12 papers, 2010 to 2025). "Prior studies have demonstrated that GBP1 interaction with SP1 promotes STAT3 activation, which enhances proliferation and invasion in cutaneous squamous cell carcinoma." (PMID 40975978, 2025). "The 5-ALA-AuNP conjugates significantly impact the STAT3 signaling pathway as depicted with reduced expression of STAT3 and Bcl-2 and high expression of Bax in the cutaneous squamous cell carcinoma cells the PDT with the free 5-ALA." (PMID 36230480, 2022). "In this study, we examined the role and related signaling molecules of Stat3 in the carcinogenesis of human cutaneous squamous cell carcinoma (SCC)." (PMID 21197106, 2011). "Stat3 activation has important implications in the cell proliferation of cutaneous squamous cell carcinoma (SCC)." (PMID 21197106, 2011). "PRECSIT promotes the progression of cutaneous squamous cell carcinoma via STAT3 signaling." (PMID 35047414, 2021). "Previous reports have suggested that STAT3 inhibition in cutaneous squamous cell carcinoma induces senescence and not apoptosis." (PMID 24423131, 2013).
Glucose intolerance (12 papers, 2005 to 2025). Glucose intolerance (GI) can be defined as dysglycemia that comprises both prediabetes and diabetes. "Talin-1 deficiency impairs β-cell proliferation at least in part by decreasing Stat3 protein, resulting in reduced β-cell mass and insulin secretion, and glucose intolerance in mice." (PMID 37903776, 2023). "We observed improvement in IL-6-induced glucose intolerance by RNAi-mediated silencing of STAT3, suggesting that silencing of the STAT3 gene exerts positive effects on glucose homeostasis." (PMID 28706484, 2017). "Pancreas-specific STAT3-KO mice exhibit glucose intolerance and impaired insulin secretion in vivo, along with microvascular alterations in the pancreas." (PMID 23923060, 2013). "The liver-specific STAT3 knockout mouse is insulin resistant and develops glucose intolerance when fed a high-fat diet, due in part to increased expression of PCK1 and G6P." (PMID 15985155, 2005). "Therefore, our current study supports that the glucose intolerance and in vivo insulin secretion defect in pancreas-specific STAT3-KO mice is due to altered microvasculature in the pancreas, and not intrinsic beta-cell function." (PMID 23923060, 2013). "To examine the role of STAT3 and TLR4 in the development of glucose intolerance, we tested IL-6-induced insulin-stimulated uptake of 2-NBDG in the skeletal muscle." (PMID 28706484, 2017). "Adenoviral mediated reconstitution of STAT3 signaling ameliorated glucose intolerance in both L-ST3KO and Lepr-/- mice by lowering PCK1 and G6P levels, demonstrating the importance of STAT3 signalling to hepatic glucose output." (PMID 15985155, 2005). "Additionally, mice with haploinsufficiency of Talin-1 and Stat3 genes, but not that of either gene, in β-cells exhibit significant glucose intolerance and reduced insulin expression, suggesting that both factors function in the same genetic pathway." (PMID 37903776, 2023). "Finally, inhibition of brain STAT3 signaling by i.c.v. treatment with AG490 normalized peripheral glucose tolerance in AβO-infused mice, and i.c.v. treatment with anti-IL-6 reversed glucose intolerance in APP/PS1 mice." (PMID 33911072, 2021).
gout (12 papers, 2020 to 2025). A condition characterized by painful swelling of the joints, which is caused by deposition of urate crystals. "IL‐6 activates STAT3 to promote neutrophil infiltration and joint inflammation, while SOCS3, a negative regulator of STAT3, is upregulated during gout flares, potentially mitigating inflammation by suppressing STAT3 signaling." (PMID 40613560, 2025). "The therapeutic targets through which Simiao decoction alleviated gouty arthritis were p-STAT3, APOB, CASP8, c-FOS, PPARα, FN1, and LPL." (PMID 32670069, 2020). "The STAT family (STAT1/STAT3/STAT4) mediates cytokine signaling in gout pathogenesis." (PMID 40613560, 2025). "Therefore, in the present study, the underlying protective role and mechanism of ELB involved in TLR4/NF-κB, NLRP3, and JAK2/STAT3 inflammatory signaling pathways were investigated in chronic alcoholic liver injury combined with gouty arthritis." (PMID 36176434, 2022). "During gout flare-ups, the JAK2/STAT3 signaling pathway is activated, leading to increased expression of cytokines such as IL-6, IL-1β, and TNF-α in both the kidneys and joints." (PMID 39611154, 2024). "During gout flare-ups, the activation of JAK2/STAT3 signaling results in an elevation of cytokine expression, including IL-6, IL-1β, and TNF-α, within the kidneys and joints." (PMID 38094893, 2023). "Lagotis brachystachya Maxim., primarily employed for treating yellow water disease (gouty arthritis) and hepatitis, is capable of reducing the expression of phospho-JAK2 and phospho-STAT3." (PMID 38094893, 2023). "The results showed that key transcription factors such as CEBPB, STAT3, RELA, and NFKB1 may be involved in the pathogenesis of gout by directly regulating the transcriptional levels of these genes." (PMID 40606658, 2025). "Studies have shown that the absence of HDAC3 in macrophages alleviates MSU crystal-induced gout inflammation by inhibiting the TLR2/4-driven IL-6/STAT3 signaling pathway, suggesting that HDAC3 may serve as a potential therapeutic target for gout." (PMID 41311848, 2025). "Deficiency of HDAC3 in macrophage alleviates MSU crystals-induced gouty inflammation through inhibition of TLR2/4 driven IL-6/STAT3 signaling pathway, suggesting that HDAC3 could contribute to a potential therapeutic target of gout." (PMID 38711064, 2024). "For example, targeting the JAK2/STAT3 signaling pathway could reduce the expression of pro-inflammatory cytokines like IL-6, IL-1β, and TNF-α, thereby alleviating gout symptoms and slowing disease progression." (PMID 39611154, 2024).
Huntington disease (12 papers, 2016 to 2025). Huntington disease (HD) is a rare neurodegenerative disorder of the central nervous system characterized by unwanted choreatic movements, behavioral and psychiatric disturbances and dementia. "Abnormal activation of STAT3 signaling was recently found to be associated with neurodegenerative disorders such as Huntington’s disease or Alzheimer’s disease." (PMID 38302598, 2024). "A recent study in Huntington’s disease patients showed that reactive astrocytes activated via the JAK2/STAT3 pathway were able to reduce the toxic huntingtin protein aggregation in neurons." (PMID 37219933, 2023). "IL-6-mediated JAK2/STAT3 signaling cascade has been shown to contribute to neurodegeneration in AD and Huntington’s disease models." (PMID 33494411, 2021). "Jak-Stat signaling, including Stat3, is up-regulated in prion, Alzheimer’s, and Huntington’s diseases, and promotes astrogliosis in scrapie-infected mice." (PMID 31959236, 2020). "Herein, we report that MC could ameliorate Huntington’s disease through its anti-inflammatory effects by inhibiting STAT3 pathways." (PMID 36899922, 2023). "In Huntington’s disease, for example, activation of JAK/STAT3 signaling improves proteostasis by increasing gene expression in proteasome and lysosomal pathways." (PMID 37048051, 2023). "Aberrant signal transducer and activator of transcription 3 (STAT3) signal activation is also relevant to neurodegenerative diseases, including AD and Huntington disease." (PMID 34837964, 2021).
nephritis (12 papers, 2008 to 2025). Inflammation of renal tissue. "Accumulating evidence suggests that the limitation of the NLRP3 inflammasome and JAK2/STAT3 signaling contributes to attenuate kidney inflammation." (PMID 41278550, 2025). "The overactive expression of STAT1 and STAT3, as well as the activated JAK–STAT signalling transduction, has been implicated in the progression of nephritis and the onset of proteinuria." (PMID 39245800, 2024). "The study indicates that circ_0007059 protects RMCs against apoptosis and inflammation during nephritis by attenuating miR-1278/SHP-1/STAT3 signaling." (PMID 34535085, 2021). "Previous studies in MRL/lpr mice inhibiting STAT3 saw decreased anti-dsDNA antibodies and nephritis, as well as decreased renal tubulointerstitial lesions." (PMID 34868008, 2021). "To determine the effect of glucocorticoids on EGFR/STAT3 signaling in anti-GBM nephritis, we performed immunohistochemical staining of phosphorylated EGFR and STAT3 in the renal biopsies of the patients with (n = 22) and without (n = 12) glucocorticoids treatment." (PMID 35223886, 2022). "In addition, STAT3 phosphorylation was found reduced by the overexpressed of circ_0007059, protecting cell viability and reducing inflammation in a nephritis cell model." (PMID 36536378, 2022). "By investigating multiple inflammatory mediators (CD93, CD36, STAT3, NF-Kappa B, and TLR2/4), our results highlight the therapeutic potential of hAAT in treating kidney inflammation." (PMID 40723823, 2025). "Reflecting the pro-inflammatory functions of nephritis, genes such as JAK3, STAT3 and MAPK1 involved in signalling pathways (JAK/STAT, MAP kinase, antigen presentation, IL1/IL10) are expressed at higher levels in the disease state." (PMID 18980674, 2008). "Increased levels of transcripts for pathway members including JAK3, STAT3, SOCS3, PTPN1, CDKN1A, RRAS and MAPK1 were observed in nephritis." (PMID 18980674, 2008).
non-alcoholic fatty liver disease (12 papers, 2018 to 2026). "Consistently, genetic variants in STAT3 were associated with non-alcoholic fatty liver disease in humans." (PMID 30038584, 2018). "BP attenuates the severity of colorectal inflammation and liver injuries caused by exposure to dextran sulfate sodium and mitigates nonalcoholic fatty liver disease via JAK1/STAT3/BAX signaling." (PMID 33971886, 2021). "Considering its potential effects on inflammatory macrophages and HSCs, STAT3 pathway is also a promising therapeutic target that can be explored in non‐alcoholic fatty liver disease (NAFLD), one of the most common liver‐related complications worldwide." (PMID 32123858, 2020). "Similarly, in metabolic diseases, such as nonalcoholic fatty liver disease, STAT3 has been implicated in immune cell infiltration and inflammatory regulation through modulation of the GCSFR-SOCS3-JAK-STAT3 signaling pathway." (PMID 40918404, 2025). "STAT3 plays a key role in the process of leptin resistance, and high leptin levels may be related to the increase of nonalcoholic fatty liver disease." (PMID 35154322, 2022). "In nonalcoholic fatty liver disease, phosphorylated HSP25 is able to interact with STAT3 (Signal transducer and activator of transcription 3), thereby stimulating autophagy and lipid droplet clearance." (PMID 37108621, 2023). "AST modulates the signaling pathways that regulate autophagy, either by stimulation as shown in an experimental model of non-alcoholic fatty liver disease, or by inhibition as shown in the pancreas by inhibiting the JAK/STAT3 pathway." (PMID 33509300, 2021).
polycystic ovary syndrome (12 papers, 2018 to 2026). A disorder that manifests as multiple cysts on the ovaries. "For instance, total flavonoids regulated serum levels of FSH, luteinizing hormone (LH), and testosterone (T) in polycystic ovary syndrome rats by inhibiting the JAK2/STAT3 pathway." (PMID 32477106, 2020). "Previous studies have found that lower levels of phosphorylated STAT3 in GCs may be related to ovarian leptin resistance and decreased fertilization in polycystic ovarian syndrome women." (PMID 29899261, 2018). "LEP is a regulatory molecule involved in the polycystic ovary syndrome (PCOS) cell model and acts as an upstream regulator of JAK1/STAT3-related inflammation and apoptosis in insulin-treated ovarian granulosa cells (OGCs)." (PMID 38005265, 2023). "Aberrant STAT3 regulation has been related with autoimmune, inflammatory disorders, such as rheumatoid arthritis, multiple sclerosis, and inflammatory bowel disease, as well as with the pathobiology of advanced glycation end products (AGEs) in polycystic ovary syndrome (PCOS)." (PMID 34440220, 2021).
rectal cancer (12 papers, 2017 to 2025). A primary or metastatic malignant neoplasm that affects the rectum. "Using cBioportal, we evaluated 18 studies of colon and rectal cancers with 7162 patients to investigate the mutational frequency of E616del; we found that only 4 patients had this STAT3 mutation." (PMID 38992681, 2024). "We recently demonstrated that perturbation of STAT3 signaling using either RNAi or the STAT3 inhibitor napabucasin re-sensitized treatment-refractory rectal cancer cells to CRT and abolished tumor growth in vivo." (PMID 35267609, 2022). "Piperine can reverse the biomarkers of EMT and inhibit the regulator of EMT, while the activation of STAT3 is down-regulated by piperine, which further inhibits the migration and invasion ability of rectal cancer." (PMID 36686745, 2022). "To now delineate how inflammatory signals control CRT resistance, we analyzed how STAT3 pathway perturbation affects the global transcriptional activity of rectal cancer cells." (PMID 33530306, 2021). "Vice versa, inhibition of the gp130/STAT3 signaling at different levels re-sensitized otherwise resistant rectal cancer cells to CRT in our cell culture systems as well as in our in vivo xenograft tumor model." (PMID 33530306, 2021). "Mechanistically, phospho-STAT3 executed CRT resistance in rectal cancer cells by supporting NOTCH signaling, specifically by stimulating expression of RBPJ, the key transcriptional effector of the NOTCH pathway." (PMID 33530306, 2021). "We now show that the tonic activity of STAT3 in rectal cancer cells is key to their resistance to CRT." (PMID 33530306, 2021). "The study has reported that the potential role of STAT3 in mediating therapeutic resistance and demonstrated for the first time that STAT3 represents a promising novel molecular target for sensitizing drug-resistant rectal cancer to chemoradiotherapy." (PMID 35698571, 2022). "Moreover, genetic profiling of rectal cancer patients revealed the importance of the STAT3/NOTCH axis as NOTCH expression correlated with clinical outcome." (PMID 33530306, 2021). "In summary, the extent of CRT resistance in human rectal cancer cells could be tuned in both directions by manipulating the activity of the IL6/STAT3 signaling pathway." (PMID 33530306, 2021). "Similarly, in rectal cancers, patients with tumors positive for phosphorylated STAT3 had improved survival outcomes." (PMID 31684858, 2019). "In combination with our detailed molecular analyses, they strongly indicate that the interplay between inflammatory gp130/STAT3 signaling and the NOTCH pathway has a central role in mediating CRT resistance in rectal cancer." (PMID 33530306, 2021). "Previously, we have demonstrated that the IL-6/STAT3 signaling pathway plays a central role in mediating the resistance of rectal cancer to chemoradiotherapy (CRT) and that inhibition of IL-6/STAT3 signaling leads to the sensitization to CRT in vitro and in vivo." (PMID 35267609, 2022). "Importantly, when RBPJ expression was silenced in otherwise CRT-resistant SW837 rectal cancer cells, the cells were re-sensitized to CRT, showing that RBPJ—like STAT3—is a key determinant of CRT resistance." (PMID 33530306, 2021). "Thus, as a consequence of inflammatory STAT3 signaling NICD and RBPJ form a functional transcription factor complex in CRT-resistant rectal cancer cells." (PMID 33530306, 2021).